RNU6-944P (RNA, U6 small nuclear 944, pseudogene)
Gene: Small nuclear RNA gene on chromosome 16 (20,784,509 to 20,784,615, forward strand). Ensembl gene ENSG00000200893.
Homologues: Orthologues: chimpanzee U6 (99% identical), macaque U6 (93% identical), guinea pig U6 (82% identical), dog U6 (81% identical), dog U6 (75% identical). Paralogues in human: RNU6-1243P (89% identical), RNU6-1287P (88% identical), RNU6-1331P (88% identical), RNU6-196P (88% identical), RNU6-797P (88% identical), RNU6-1091P (87% identical), RNU6-43P (87% identical), RNU6-445P (87% identical), RNU6-511P (87% identical), RNU6-698P (87% identical), RNU6-727P (87% identical), RNU6-1060P (86% identical), and 1287 more.